DICER1 (dicer 1, ribonuclease III)
Diseases named in the same sentence as DICER1 in open-access papers (continued):
Sharing a sentence is not in itself a finding about the gene and the disease.
neuroblastoma (10 papers, 2013 to 2022). Neuroblastoma (NB) is the most common solid, extracranial childhood tumor. "To further investigate the biallelic Dicer1 mutation, we Sanger sequenced the DICER1 RNAse IIIb domain in 155 primary neuroblastoma cases and the frequently mutated catalytic hotspot in an additional 121 cases." (PMID 29492199, 2018). "The neuroblastoma driving potential of LIN28B and the occurrence of a bi-allelic Dicer1 RNAse IIIb domain mutation is indicative of the importance of miRNA deregulation in neuroblastoma tumor formation." (PMID 29492199, 2018). "The association of neuroblastoma and DICER1 variation is unsettled." (PMID 30672147, 2019). "In addition, a truncating mutation in DICER1 was described in a single case of human neuroblastoma analyzed by whole genome sequencing." (PMID 29492199, 2018). "MOV10 and FMRP modulate expression of DICER1 mRNA through its 3’untranslated region (UTR) and introduction of a DICER1 transgene restores normal neurite outgrowth in the Mov10 KO neuroblastoma Neuro2A cell line and branching in MOV10 heterozygote neurons." (PMID 34847178, 2021). "In keeping with this observation, DICER1 is located in chromosome band 14q32.13, a region which is known to be frequently affected by deletions in neuroblastoma and other tumors." (PMID 29492199, 2018). "A truncated DICER1 gene transcript that misses part of the RNAse IIIb domain has been reported in neuroblastoma cells." (PMID 29492199, 2018). "Prior to initiating the in vivo studies, the effectiveness of an EmGFP-Dicer1 shRNA cassette to knockdown Dicer1 mRNA was tested by transducing mouse N1E-115 neuroblastoma cells." (PMID 27047334, 2016). "We used computational prediction to identify potential miRs down-regulating Dicer1 in neuroblastoma." (PMID 24223844, 2013). "Although they do occur, our data clearly shows that DICER1 mutations are not a major mechanism of miRNA biogenesis alteration in neuroblastoma." (PMID 29492199, 2018). "Moreover, in neuroblastoma, DICER1 and ARGONAUTE RNA expression levels have been shown to correlate with survival, with lower expression levels occurring in high-risk tumors." (PMID 29492199, 2018). "Comparative cross species analysis of all 25 non-synonymous coding mutated genes detected in the mouse models resulted in three matches (DICER1, ZNF574 and PTCH1) in the list of 883 genes reported to harbor non-synonymous coding mutations in human neuroblastoma." (PMID 29492199, 2018). "This study aimed to investigate the mechanisms that could lead to the down-regulation of Dicer1 in neuroblastoma." (PMID 24223844, 2013). "Similarly, the frequency of neuroblastoma arising from mosaic DICER1 hotspot missense variation is unknown." (PMID 30672147, 2019). "No other DICER1 gene mutations have been reported in other neuroblastoma sequencing efforts." (PMID 29492199, 2018). "In two large (n = 240; n = 71) somatic sequencing studies of neuroblastoma, no somatic DICER1 variation was observed." (PMID 30672147, 2019).
age-related macular degeneration (9 papers, 2013 to 2023). Age-related loss of vision in the central portion of the retina (macula), secondary to retinal degeneration. "Loss of DICER1 function is associated with the accumulation of Alumers and inflammasome activation, leading to age-related macular degeneration (AMRD)." (PMID 30729177, 2019). "Loss of DICER1 function produces age-related macular degeneration, a different type of Alu-mediated disease." (PMID 30729177, 2019). "Donor human eyes with geographic atrophy, a form of age-related macular degeneration, was reported to have reduced DICER1 mRNA in macular RPE." (PMID 37099569, 2023). "DICER1 deficiency in the retinal pigment epithelium (RPE) was associated with the accumulation of Alu transcripts and implicated in geographic atrophy (GA), a form of age-related macular degeneration (AMD), an eye disease leading to blindness in millions of people." (PMID 32765950, 2020). "Recently studies suggest DICER1 plays an important role in the pathogenesis of dry age-related macular degeneration (AMD)." (PMID 26124959, 2015). "DICER1 was recently shown to have another function of silencing the toxicity of Alu RNAs in retinal pigment epithelium (RPE) cells, which are involved in the pathogenesis of age related macular degeneration." (PMID 26124959, 2015).
diabetes (9 papers, 2011 to 2025). "In this sense, common variants in DICER1, such as rs13078, rs105703, and rs3742330, have been associated with a variety of human illnesses, including cancer, diabetes, cardiovascular, autoimmune, and neurodegenerative diseases." (PMID 39202414, 2024). "For instance, variants rs7813 in GEMIN4 and rs636832 in AGO1 have been associated with an increased risk of the multiple sclerosis variant, whereas variant rs13078 in DICER1 has been associated with a decreased risk of type 2 diabetes mellitus." (PMID 39202414, 2024). "To investigate the effect of Dicer1 deficiency on diabetes development, we generated mice with a β-cell specific Dicer1 deletion from mid gestation (E9–11.5) using the Cre-lox system (RIP-Cre Dicer1Δ/Δ) by crossing RIP-Cre transgenic with Dicerflox/flox mice." (PMID 22216196, 2011). "By 12 weeks of age, 80% of Dicer1 deficient mice (n = 70) developed diabetes and, by 25 weeks of age, 100% of mice were diabetic." (PMID 22216196, 2011). "Likewise, deletion of Dicer1 in beta-cells leads to loss of insulin expression and the development of diabetes in adult mice." (PMID 40641525, 2025). "The dysregulation of miRNAs through Dicer1 (an essential RNase for active miRNA biogenesis) ablation in early embryonic pancreatic progenitor cells in mice results in severe deficiencies in the formation of beta-cells and the establishment of diabetes within 2 weeks of birth." (PMID 40641525, 2025). "DICER1 levels are decreased in circulating cells in patients with type 2 diabetes, and deletion of DICER1 in adipose or pancreatic islet beta cells triggers insulin resistance and diabetes in mice." (PMID 32968070, 2020). "Here, we show that metformin treatment increases the levels of the microRNA‐processing protein DICER1 in mice and in humans with diabetes mellitus." (PMID 26990999, 2016). "We found higher levels of DICER1 in mice treated with metformin or caloric restriction as well as in humans with diabetes mellitus on metformin." (PMID 26990999, 2016). "β-cells specific Dicer1 deletion results in aberrant pancreas development and neonatal death and its inactivation leads to development of diabetes due to reduced insulin expression." (PMID 23878802, 2013). "Targeted disruption of the Dicer1 gene specifically in β-cells leads to progressive reduction in insulin secretion and glucose tolerance and development of diabetes." (PMID 23878802, 2013). "We have studied the role of miRNAs in β-cell function and in the development of diabetes in vivo by specifically deleting Dicer1 in pancreatic β-cells under the RIP-promoter." (PMID 22216196, 2011). "Inactivation of Dicer1 in adult life leads to development of diabetes due to reduced insulin expression." (PMID 22216196, 2011). "In this work, we demonstrate for the first time that targeted disruption of the Dicer1 gene specifically in β-cells leads to progressive reduction in insulin secretion, glucose tolerance and development of diabetes." (PMID 22216196, 2011). "Metformin administration has been associated with the altered expression of miR-26a in pancreatic cancer stem cell markers, miR-221 and miR-222 in patients with diabetes mellitus type 2 and DICER1 in a novel therapeutic approach for age-related health problems." (PMID 36009364, 2022). "Interestingly, DICER1 levels are decreased in circulating cells in patients with type 2 diabetes, and deletion of DICER1 in adipose or pancreatic islet beta cells triggers insulin resistance and diabetes in mice." (PMID 32968070, 2020). "The effects of RAN, XPO5, DICER1, and TARBP2 SNPs on diabetes progression were further analyzed." (PMID 31354628, 2019). "Our study may provide a new clue of epidemiology about the importance of miRNA processing genes (RAN, XPO5, DICER1, and TARBP2) in type 2 diabetes mellitus and diabetic vascular complications." (PMID 31354628, 2019). "Additionally, lack of Dicer1 in beta-cells leads to impaired insulin signaling and promotes the development of diabetes." (PMID 34483928, 2021).
follicular adenoma (9 papers, 2018 to 2026). "C Case KI 8 at × 40 magnification, a macrofollicular variant follicular thyroid adenoma with somatic DICER1 mutation." (PMID 38637342, 2024). "Coexistent nodular hyperplasia and follicular adenoma were significantly more frequent in DICER1-mutated FC compared to those without the mutation; another observation was that all cases of FC in children less than 10-years of age at diagnosis had a DICER1 mutation." (PMID 34599283, 2022). "Somatic DICER1 pathogenic variants are associated with thyroblastoma and childhood-onset PDTC, whereas germline variants are linked to TFND, follicular adenoma with papillary architecture, PTC, and FTC." (PMID 39950167, 2024). "Another clue for DICER1 mutation in the context of FVPTC is coexistent nodular hyperplasia and/or follicular adenoma." (PMID 38254836, 2024). "We also sequenced DICER1 from her thyroid follicular adenoma and bladder rhabdomyosarcoma." (PMID 31893257, 2018).
lung adenocarcinoma (9 papers, 2013 to 2025). A carcinoma that arises from the lung and is characterized by the presence of malignant glandular epithelial cells. "For example, significant changes in DICER1 expression have been detected during different stages of lung adenocarcinoma." (PMID 25883138, 2015). "Indeed this may be a wider phenomenon as other cancers such as bladder, prostate and lung adenocarcinomas also demonstrate aberrant expression of either Dicer1 or Drosha." (PMID 26867589, 2016).
oral cancer (9 papers, 2012 to 2022). "Our present study identified and characterized a 93-kDa Dicer1 protein variant, Dicer1e, in oral cancer cells." (PMID 25115815, 2014). "There are SNPs correlated to increased risk of oral cancer like rs3746444 in mir-499, rs2292832 in miR-149 and rs14035 in Ran, and there are SNPs connected to decreased risk of oral cancer such as rs11614913 in miR-196a2, rs2187473 in mir-34b and rs1057035 in DICER1." (PMID 35888762, 2022). "Moreover, another SNP located in DICER1’s 3'-UTR (rs1057035) may contribute to oral cancer risk by affecting miRNA binding to DICER1." (PMID 26147304, 2015). "The upregulation of Dicer1 in tonsillar cancers is consistent with studies in salivary pleomorphic adenomas and oral cancers." (PMID 26867589, 2016). "However, studies also demonstrated that elevated expression levels of DICER1 were correlated with increased cell proliferation of oral cancer cells." (PMID 26688807, 2015). "The transfection of an exogenous siRNA targeting Dicer1e specifically, but not Dicer1, significantly inhibited the proliferation and clonogenic potential of three separate oral cancer cell lines, by either inducing apoptosis and/or G2/M cell cycle arrest." (PMID 25115815, 2014). "Additionally, the 218-kDa Dicer1 protein was also found to be upregulated in 4 of 5 OSCC tissue samples, thus, corroborating our previous findings that oral cancer tissues have increased levels of Dicer1." (PMID 25115815, 2014).
ovarian sex cord-stromal tumor (9 papers, 2015 to 2025). A benign or malignant neoplasm that arises from the ovary and is composed of granulosa cells, Sertoli cells, Leydig cells, theca cells, and fibroblasts. "Beyond ovarian sex-cord stromal tumors, pathogenic germline DICER1 variants are associated with benign and malignant tumors of the lung, thyroid, kidney, and central nervous system as part of an autosomal dominant tumor predisposition syndrome." (PMID 41416308, 2025). "JGCT is another type of ovarian sex-cord stromal tumor that has been rarely associated with germline DICER1 pathogenic variants." (PMID 40076617, 2025). "We have previously reported DICER1 RNase IIIb mutations in sex-cord stromal tumors of the ovary and in about 0.6% of EC." (PMID 33052929, 2020). "Additionally, several studies have confirmed that UTROSCT lacks the characteristic JAZF-1-SUZ12 gene fusion or PHF1 gene rearrangement of endometrial stromal tumors and does not have the FOXL2 and DICER1 gene mutations unique to ovarian sex cord stromal tumors." (PMID 40417005, 2025). "However, molecular alternations are different than those usually observed in ovarian sex cord stromal tumors (e.g., no FOXL2 nor DICER1 variants)." (PMID 38136408, 2023).
pancreatic cancer (9 papers, 2017 to 2025). "Probably, a current hot topic is the onset of pancreatic cancer associated with DICER1." (PMID 39857323, 2025). "The observation that the level of mature, functional miR-200s may be impacted by the MCPiP1/Dicer1 ratio provides new insight into the mechanism responsible of the loss of miR-200s, and consequently of tumor progression and chemoresistance in pancreatic cancers." (PMID 30542509, 2018). "In details, miR-548b-3p of the first closed group regulated DICER1, involved in the biogenesis of miRNAs themselves;Recently, a potential oncogenic role for DICER1 in pancreatic cancer initiation was also reported." (PMID 29285254, 2017). "In pancreatic cancer cells, MCPIP1 decreases the expression of miR-200 family members through counteracting Dicer1 in miRNA maturation process." (PMID 34021267, 2021). "Even if there are not many pancreatic tumors that start in the endocrine system, we still need to undertake additional research to find out if DICER1 is a good therapeutic target." (PMID 39857323, 2025). "Moreover, another lncRNA called antisense RNA1 of DICER1 (DICER1-AS1), which is downregulated in pancreatic cancer (PC) tissues and overexpression of DICER1-AS1 inhibits glycolysis, proliferation and metastasis of PC cells both in vitro and in vivo." (PMID 37069649, 2023).
schizophrenia (9 papers, 2015 to 2025). A major psychotic disorder characterized by abnormalities in the perception or expression of reality. "An SNP (rs3742330) of DICER1 was reported to be associated with Chinese schizophrenia, and a rare missense mutation of DICER1 was detected in a Chinese patient with schizophrenia." (PMID 35743796, 2022). "Hence, DICER1 was considered a susceptibility gene for schizophrenia." (PMID 35743796, 2022). "The same gene, DICER1, was overexpressed in the dorsolateral prefrontal cortex of schizophrenia patients." (PMID 41191625, 2025). "Genetic association studies have reported associations between SNPs in DGCR8 (rs3757, rs8139591, rs9606248) and the pre-miRNA processing gene DICER1 (rs3742330, rs11621737) and the incidence of schizophrenia in Han Chinese patients." (PMID 29657307, 2018). "In Brodmann area (BA) 9 of the DLPFC, DGCR8, DROSHA, and DICER1 have all be reported to be increased in schizophrenia with other miRNA processing proteins, such as XPO5, which is reported as unchanged." (PMID 29657307, 2018). "By contrast, in the adjacent BA 46 of the DLPFC, only DICER1 mRNA is shown to be significantly upregulated in in schizophrenia." (PMID 29657307, 2018). "Of 8 genes showing more than two supporting evidences for pathogenic prediction, some of genes (e.g. LRP1, MACF1, DICER1 and ABCA2) harbours de novo mutations provided promising evidence as a strong candidate genes for schizophrenia." (PMID 26666178, 2015). "Notably, the increased expression of DICER1 in the dorsolateral frontal cortex was reported in patients with schizophrenia." (PMID 35743796, 2022). "However, in a more recent study, the authors suggested that a Dicer1 dependent disruption of miRNA biogenesis may play a role in schizophrenia pathogenesis." (PMID 34954808, 2022). "Remarkably, in individuals with schizophrenia, we report DICER1 overexpression in the dorsolateral prefrontal cortex, hippocampus and cerebellum as well as a congruent DICER1 upregulation in the blood compartment suggesting that it may represent a peripheral marker." (PMID 33149139, 2020). "For instance, a Dicer1 dependent disruption of miRNA biogenesis and the lack of GABRB2 expression have been linked to schizophrenia pathogenesis." (PMID 34954808, 2022).
cervical carcinoma (8 papers, 2013 to 2023). A carcinoma arising from either the exocervical squamous epithelium or the endocervical glandular epithelium. "miR-130a directly targets DICER1 mRNA to enhance SiHa cell (cervical cancer cells) migration and invasion." (PMID 37495108, 2023). "Similarly, lower mRNA expression levels of DICER1 were found in cervical cancer; however, the mechanisms of its down-regulation in cervical cancer are still unclear." (PMID 29853562, 2018). "For example, increased DICER1 and DROSHA mRNA expression were found in some human papillomavirus (HPV) positive cervical cancer cell lines." (PMID 37243263, 2023). "The lower expression level of the Dicer protein compared with that of Dicer mRNA in cervical cancer might be mediated by protein regulation; for example, reduced levels of the TRBP protein, an integral component of the DICER1-containing complex, resulted in a destabilization of the DICER1 protein." (PMID 24787017, 2014).
glioblastoma (8 papers, 2016 to 2026). The most malignant astrocytic tumor (WHO grade IV). "In glioblastoma, reduced miRNA abundance compared to normal brain tissue has been associated with an aberrant nuclear localization of DICER1 (dicer 1 ribonuclease III, a crucial endonuclease for miRNA maturation)." (PMID 39966624, 2025).
non-small cell lung carcinoma (8 papers, 2008 to 2024). A group of at least three distinct histological types of lung cancer, including non-small cell squamous cell carcinoma, adenocarcinoma, and large cell carcinoma. "Using a CRISPR/Cas9 toolkit we engineered phenotypically diverse non-small cell lung cancer (NSCLC) cells by conferring mutations in Dicer1, a type III cytoplasmic endoribonuclease involved in small non-coding RNA genesis." (PMID 31449515, 2019). "We have previously demonstrated the role of DICER1 in the development of prostate adenocarcinoma and non-small cell lung carcinoma." (PMID 19578509, 2008). "The combination of two miRNA biogenesis genes (DICER1 and DROSHA) and four miRNAs (miR-30d, miR-21, miR-17, and miR-155) is one of the putative predictive indicators in non-small cell lung cancer." (PMID 39132504, 2024). "In cancer, miR-130a targets MET in non-small cell lung carcinoma and can target ATG2B and DICER1 to kill Chronic Lymphocytic Leukemia cells." (PMID 24885472, 2014).